MIR17HG (miR-17-92a-1 cluster host gene)
Synonyms: C13orf25; MIRH1; MIRHG1; FLJ14178; MIHG1; NCRNA00048; miR-17-92; LINC00048
Gene: Long non-coding RNA gene on chromosome 13 (91,347,686 to 91,397,592, forward strand). Ensembl gene ENSG00000215417.
Subcellular location: Membrane
Gene Ontology:
Biological process: miRNA-mediated post-transcriptional gene silencing
Cellular component: RISC complex
Diseases named in the same sentence as MIR17HG in open-access papers:
MIR17HG is named in the same sentence as 56 diseases in open-access papers, as found by Europe PMC text mining. Sharing a sentence is not in itself a finding about the gene and the disease. The quoted sentences say what the papers report.
colorectal cancer (10 papers, 2019 to 2023). A primary or metastatic malignant neoplasm that affects the colon or rectum. "In conclusion, this study provides the first evidence that the polymorphisms (rs7336610, rs7318578, rs17735387, and rs1428) of MIR17HG were associated with colorectal cancer risk." (PMID 30941921, 2019). "In this study, we recruited 514 patients with colorectal cancer and 510 healthy controls to investigate the association between polymorphisms (rs72640334, rs7336610, rs7318578, rs17735387, and rs1428) of MIR17HG and risk of colorectal cancer in the Chinese Han population." (PMID 30941921, 2019). "The results indicated that the two SNPs (rs7336610 and rs1428) of MIR17HG were associated with increased colorectal cancer risk, but the two SNPs (rs7318578, rs17735387) of MIR17HG were associated with decreased colorectal cancer risk in the Chinese Han population." (PMID 30941921, 2019). "For example, LINC00857 contributes to diffuse large B-cell lymphoma proliferation and lymphomagenesis by sponging miR-370-3p, while lncRNA MIR17HG promotes colorectal cancer liver metastasis by sponging miR-138-5p." (PMID 35017465, 2022). "miR-17-5p is also regulated by other lncRNAs or target other mRNAs and then, promotes tumorigenesis, for example, MIR17HG promotes colorectal cancer progression via miR-17-5p, miR-17-5p promotes angiogenesis in nasopharyngeal carcinoma via targeting BAMBI." (PMID 35365175, 2022). "Overexpression of PART1, SNHG11, LINC00173 and MIR17HG is widely involved in tumorigenesis and malignant progression of several types of cancer, such as glioma, breast cancer, lung cancer and colorectal cancer." (PMID 34243770, 2021). "According to a growing body of evidence, MIR17HG may interact with the corresponding mRNA via the ceRNA mechanism in many cancers such as colorectal cancer and gastric cancer." (PMID 36943627, 2023). "Demonstrate that MIR17HG plays an oncogenic role in colorectal cancer." (PMID 35249533, 2022). "Consistent with our result, a previous study showed that β-catenin and TCF4, a member of T-cell and lymphoid enhancer (TCF/LEF) factor family, could bind to and regulate MIR17HG promoter in colorectal cancer." (PMID 31191623, 2019).
breast carcinoma (7 papers, 2014 to 2023). "MIR17HG overexpression caused G2/M arrest in breast cancer cells according to a flow cytometry assay." (PMID 36943627, 2023). "Further studies found that increased MIR17HG expression is associated with a poor prognosis in patients with diverse types of tumours, and single-nucleotide polymorphisms of MIR17HG are associated with a risk of breast cancer development." (PMID 31186404, 2019). "MIR17HG downregulation during metastatic progression is also congruent with the reported inverse correlation between expression of miR-92a, another member encoded by MIR17HG, and the tumor grade and recurrence-free survival of breast cancer patients." (PMID 25069832, 2014). "We found that miR-18a, along with other family members encoded by MIR17HG, was downregulated in breast cancer cells that spontaneously metastasized to lungs in an orthotopic xenograft model." (PMID 25069832, 2014). "In transwell experiments, MIR17HG knockdown was linked to enhanced breast cancer cell migration." (PMID 36943627, 2023). "The level of MIR17HG expression in breast cancer patients is linked to lymph node metastasis." (PMID 36943627, 2023). "In order to investigate the association between the expression level of MIR17HG and the clinicopathological characteristics of breast cancer patients, the TCGA database was utilized to evaluate the link between the expression level of MIR17HG and the survival rate of breast cancer patients." (PMID 36943627, 2023). "Nonetheless, our study suggests that MIR17HG is a key signaling molecule that functions to inhibit cell migration in breast cancer, providing the foundation for its development as a novel biomarker in breast tumors." (PMID 36943627, 2023). "The goal of this research is to look at the interaction between MIR17HG and FAM135A expression in breast cancer cells, as well as the link between MIR17HG expression and breast cancer cell proliferation and migration, as well as possible mechanism." (PMID 36943627, 2023). "MIR17HG, a breast cancer-related lncRNA, was shown to be considerably down-regulated in breast cancer tissues and cells in this study, and its low expression was linked to advanced TNM stage, tumor volume expansion, and survival rate." (PMID 36943627, 2023). "MIR17HG knockdown reduces FAM135A mRNA expression in breast cancer cells, but MIR17HG overexpression enhances FAM135A mRNA expression." (PMID 36943627, 2023). "The miR-454-3p expression in breast cancer cells increases when MIR17HG is knocked down, and when MIR17HG is overexpressed, the amount of miR-454-3p expressed out to be decreasing in breast cancer cells." (PMID 36943627, 2023). "MIR17HG expression was shown to be lower in human breast cancer tissues as compared to the control group." (PMID 36943627, 2023). "MIR17HG expression is reduced in breast cancer tissues, and patients with greater levels of MIR17HG expression have a better prognosis." (PMID 36943627, 2023). "To investigate MIR17HG’s role in breast cancer, we used shRNA technology to knock it down in MCF-7 cells." (PMID 36943627, 2023). "Then, using wound healing assays, we show that MIR17HG overexpression reduces breast cancer cells’ ability to migrate, which is consistent with our prior experimental findings." (PMID 36943627, 2023). "The expression of MIR17HG in breast cancer tissue was investigated to see if it plays a role in the disease." (PMID 36943627, 2023). "Our findings reveal the function of MIR17HG/miR-454-3p/FAM135A axis in breast cancer and provide potential novel therapeutic targets for metastatic breast cancer intervention." (PMID 36943627, 2023). "MIR17HG is a tumor suppressor gene in breast cancer, according to our results." (PMID 36943627, 2023). "In addition, MIR17HG overexpression was found to inhibit proliferation of luminal breast cancer cells by targeting a steroid receptor coactivator (NCOA3), cyclin D1 (CCND1) and estrogen receptor α (ESR1)." (PMID 25069832, 2014).
breast carcinoma (continued). "Therefore, we hypothesized that MIR17HG also regulates the development of breast cancer cells and thus affects the prognosis of breast cancer patients through the ceRNA mechanism." (PMID 36943627, 2023). "Our findings demonstrated that MIR17HG might suppress breast cancer cell proliferation and migration by sponge miR-454-3p through ceRNA(competing endogenous RNAs) mechanism, indicating that targeting MIR17HG may be a feasible therapeutic candidate for breast cancer." (PMID 36943627, 2023). "These novel findings indicate that MIR17HG may be a potential target for breast cancer." (PMID 36943627, 2023). "In this study, we discovered that MIR17HG/miR-454-3p/FAM135A axis functions in preventing development and metastasis in breast cancer." (PMID 36943627, 2023). "From our analysis, several members of this polycistron were hypomethylated, including MIR17HG, a known promoter of tumorigenesis and metastasis in CRC, miR-18a (miR-18a) having been shown to be important in prostate cancer, breast cancers, osteosarcoma, and nasopharyngeal carcinoma." (PMID 34885060, 2021).
glioma (7 papers, 2018 to 2025). A benign or malignant brain and spinal cord tumor that arises from glial cells (astrocytes, oligodendrocytes, ependymal cells). "In conclusion, we reported that MIR17HG rs7318578 might be a risk factor for the susceptibility of glioma and rs17735387 was associated with the longer survival of glioma among Chinese Han population." (PMID 33036577, 2020). "Our study firstly provided evidence about the effect of MIR17HG polymorphisms on the risk and prognosis of glioma, which might help to enhance the understanding of MIR17HG gene in gliomagenesis." (PMID 33036577, 2020). "Our study firstly reported that MIR17HG rs7318578 was a risk factor for glioma susceptibility and rs17735387 was associated with the longer survival of glioma among Chinese Han population, which might help to enhance the understanding of MIR17HG gene in gliomagenesis." (PMID 33036577, 2020). "Cell Counting Kit-8, transwell assays, and flow cytometry were used to investigate the function of FXR1 and MIR17HG in malignant biological behaviors of glioma cells." (PMID 30691465, 2019). "Stable knockdown of FXR1 and MIR17HG in glioma cells were established to explore the function of FXR1, MIR17HG in glioma cells." (PMID 30691465, 2019). "MIR17HG expression was increased and positively correlated with the progression of glioma pathological grades." (PMID 30691465, 2019). "In the present study, we found that expression of FXR1 and MIR17HG were elevated in glioma tissues and cells." (PMID 30691465, 2019). "Our results suggested that MIR17HG expression was positively correlated with the histopathological grade in human glioma tissues and was elevated in U87 and U251 cells." (PMID 30691465, 2019). "we investigated the expression of FXR1, MIR17HG, miR-346, miR-425-5p, TAL1 and DEC1 in glioma cells and elucidated the underlying molecular mechanisms in glioma cells." (PMID 30691465, 2019). "This suggests that MIR17HG silencing regulates the permeability of glioma-conditioned normal BBB via the paracellular pathway." (PMID 30305135, 2018). "Furthermore, MIR17HG was found to be upregulated in glioma tissues and cell lines, and its downregulation resulted in increased expression of mir‐346/mir‐425‐5p." (PMID 38321787, 2024). "MIR17HG was significantly upregulated in glioma cell lines compared with normal human astrocytes." (PMID 30691465, 2019). "Also, knockdown of MIR17HG increased suppression of glioma cell progression induced by inhibition of FXR1." (PMID 30691465, 2019). "Further, the expressions of MIR17HG in glioma tissues and cells were investigated by qPCR." (PMID 30691465, 2019). "In addition, inhibition of FXR1 combined with inhibition of MIR17HG significantly impeded glioma cell growth." (PMID 30691465, 2019). "FXR1and MIR17HG were upregulated in glioma tissues and cell lines." (PMID 30691465, 2019). "To validate whether MIR17HG could bind to miR-153 and miR-377 and regulate their expression, we first determined the expression of miR-153 and miR-377 in glioma-conditioned ECs (GECs) after silencing of MIR17HG." (PMID 30305135, 2018). "MIR17HG was expressed in both ECs and glioma-conditioned ECs (GECs)." (PMID 30305135, 2018). "Furthermore, MIR17HG knockdown inhibits the proliferation, migration, and invasion as well as promoting apoptosis in glioma cells, which indicated that MIR17HG may serve as an oncogene facilitated malignant progression of glioma cells." (PMID 30691465, 2019). "Therefore, we predicted that MIR17HG was involved in FXR1-mediated regulation on glioma cells." (PMID 30691465, 2019). "Thus, we believe that MIR17HG is likely to play a cancer-promoting role in gliomas." (PMID 30305135, 2018). "This confirmed the expression of MiR17hg, SNHG6, H19 and Pvt1 in glioma-infiltrating immune cells, consistent with our murine models." (PMID 40527978, 2025). "In the present study, we profiled the expressions of FXR1, MIR17HG, miR-346, miR-425-5p and TAL1 in glioma tissues and cells." (PMID 30691465, 2019).
glioma (continued). "FXR1/MIR17HG/miR-346(miR-425-5p)/TAL1/DEC1 axis plays a novel role in regulating the malignant behavior of glioma cells, which may be a new potential therapeutic strategy for glioma therapy." (PMID 30691465, 2019). "Moreover, compared with inhibition of FXR1 or MIR17HG alone, the inhibition of FXR1 and inhibition of MIR17HG significantly increased the expression of miR-346 and miR-425-5p, further enhanced the suppression of glioma cell malignant progression." (PMID 30691465, 2019). "The results indicate that piR-DQ590027 overexpression increases the permeability of glioma-conditioned normal BBB via the paracellular pathway by reducing the expressions of ZO-1, occludin, and claudin-5 in a manner that is related to the negative regulation of MIR17HG expression." (PMID 30305135, 2018). "However, the expression levels of Neat1, Mir142hg, Pvt1, Mir17hg, SNHG12 and Meg3 showed opposite trends, which may correlate with the distinct inflammatory profiles and immunophenotypes of the different glioma models analyzed." (PMID 40527978, 2025).
gastric cancer (6 papers, 2019 to 2024). A primary or metastatic malignant neoplasm involving the stomach. "Specially, MIR17HG has been shown to be abnormaly regulated in stomach cancer in published literature." (PMID 32216744, 2020). "MIR17HG promotes colorectal as well as gastric cancer progression and up-regulates PD-L1 expression, which could be inhibited by γ-IFN." (PMID 34336652, 2021). "Based on previous studies, we hypothesised that an investigation of MIR17HG inhibition would be beneficial to clinical gastric cancer treatment, and systematically coupled bioinformatics analyses brought interferon regulatory factor-1 (IRF-1) to our attention." (PMID 31186404, 2019). "In addition, MIR17HG can enhance the expression of mir‐18a and mir‐19a, suppress the expression of Smad2, and upregulate Wnt/β‐Catenin signaling, thereby facilitating the metastasis of gastric cancer cells." (PMID 38321787, 2024). "Moreover, IFN-γ induced the IRF-1-mediated downregulation of MIR17HG in gastric cancer cells." (PMID 31186404, 2019). "MIR17HG and MIR22HG have been wildly investigated in many cancers, including CRC, gastric cancer, and MIR17HG was also related to the paclitaxel resistance in ovarian cancer." (PMID 37245016, 2023).
lung carcinoma (3 papers, 2017 to 2021). "Another study found that overexpression of MIR17HG was involved in a negatively regulating proapoptotic gene in the occurrence of lung cancer." (PMID 33299861, 2020). "The miR-17-92 cluster (miR17-5p, miR-18, miR-19a, miR-19b, miR-20a and miR-92a), located in an intron of MIR17HG [miR-17-92 cluster host gene (non-protein coding)] on chromosome 13 (13q31.3), is overexpressed in lung cancers, especially with the most aggressive SCLC." (PMID 28410216, 2017).
adenoma (2 papers, 2023 to 2024). A neoplasm arising from the epithelium. "MIR17HG may be one of the markers for the early diagnosis of CRC to identify adenoma from adenocarcinoma because it was found that the expression of MIR17HG in colorectal adenocarcinoma was higher than that in normal tissues and adenomas." (PMID 38294554, 2024).
asthma (2 papers, 2020 to 2022). "Among the 5 key lncRNAs, MALAT1 and MIR17HG were thought to be most crucial as they linked to more verified asthma-related miRNAs and mRNAs, also, the functional enrichment results were much abundant than the other 3 lncRNAs." (PMID 31924195, 2020). "This study constructed an asthma-associated competing endogenous RNA network, determined 5 key long non-coding RNAs (MALAT1, MIR17HG, CASC2, MAGI2-AS3, DAPK1-IT1) and identified 8 potential new drugs (Tamoxifen, Ruxolitinib, Tretinoin, Quercetin, Dasatinib, Levocarnitine, Niflumic Acid, Glyburide)." (PMID 31924195, 2020). "MALAT1 and MIR17HG had many common enrichment results that were important in asthma." (PMID 31924195, 2020). "Then by utilizing bioinformatics tools, we constructed a lncRNA-miRNA-mRNA ceRNA network, from which we extracted asthma related DE ceRNA network and recognized 5 potential key lncRNAs (MALAT1, MIR17HG, CASC2, MAGI2-AS3 and DAPK1-IT1)." (PMID 31924195, 2020).
colon cancer (2 papers, 2021 to 2024). "The suppression of MIR17HG hampers colon cancer cell viability, invasion, and the EMT process, impairing in vivo tumor formation." (PMID 38534736, 2024). "Additionally, the oncogenic role of MIR17HG in colon cancer relies on activating the Wnt/β-catenin signaling pathway through upregulating miR-17 and miR-18a, further promoting disease progression." (PMID 38534736, 2024).
lymph node metastasis (2 papers, 2019 to 2023). "In addition, the trend towards a difference in lymph node metastasis between patients with different expression levels of MIR17HG was significant." (PMID 31186404, 2019).
microcephaly (2 papers, 2020 to 2023). A congenital or acquired developmental disorder in which the circumference of the head is smaller than normal for the person's age and sex. "Interestingly, we found several differentially expressed genes following infection with ZIKV Uganda, including COL4A1, MIR17HG, TUBA1A, SLC2A1 and STAMBP, which are associated with microcephaly according to the comparative toxicogenomics database." (PMID 33121145, 2020).
multiple myeloma (2 papers, 2020). "Polymorphisms (rs7336610 and rs1428), haplotype AC (rs4284505-rs1428) and CA (rs7336610-rs4284505) of MIR17HG were correlated with increased multiple myeloma risk, whereas haplotype GC (rs4284505-rs1428) significantly elevated multiple myeloma risk." (PMID 32748943, 2020).
neuroblastoma (2 papers, 2021 to 2025). Neuroblastoma (NB) is the most common solid, extracranial childhood tumor. "Given that MYCN is a known regulator of MIR17HG in neuroblastoma and medulloblastoma, we sought to determine whether MYCN is necessary for the miR-17–92 expression in these FP-RMS cells." (PMID 41473312, 2025).
non-small cell lung carcinoma (2 papers, 2021 to 2025). A group of at least three distinct histological types of lung cancer, including non-small cell squamous cell carcinoma, adenocarcinoma, and large cell carcinoma. "lncRNA miR-17-92a-1 cluster host gene (MIR17HG), upregulated in non-small cell lung cancer (NSCLC), promotes Treg-mediated immunosuppression." (PMID 41409273, 2025). "In addition, MIR17HG might exert its antitumor effect by decreasing the methylation level of miR-142-3p in non-small cell lung cancer." (PMID 34145399, 2021).
prostate carcinoma (2 papers, 2021 to 2022). A carcinoma that arises from epithelial cells of the prostate gland. "Further investigation reveals the role of AR as an upstream mediator of MIR17HG, so that silencing AR decreases MIR17HG expression in prostate cancer cells." (PMID 35317831, 2022).
alopecia areata (1 paper, 2022). Loss of scalp and body hair involving microscopically inflammatory patchy areas. "This could support the role of MIR17HG in alopecia areata pathogenesis and phenotype in the Egyptian population." (PMID 35328059, 2022).
B-cell lymphoma (1 paper, 2023). "MIR17HG encodes several micro-RNAs operating as well-known oncogenes in hematopoietic malignancies including B-cell lymphoma." (PMID 37371852, 2023). "Of note, MIR17HG was targeted in SC-1 by a focal genomic amplification at 13q21 and showed enhanced expression, indicating oncogenic activity of this micro-RNA gene in SC-1 cells and triple-hit B-cell lymphoma." (PMID 37371852, 2023).
Burkitt lymphoma (1 paper, 2020). A rare form of malignant mature B-cell non-Hodgkin lymphoma. "Similar deregulation of PTEN and MIR17HG is also in place in Burkitt lymphoma (BL) cells, in which the constitute activation of the MYC oncogene that is due to chromosomal translocation also directly activates PI3K/AKT/mTOR." (PMID 32033478, 2020).
endometriosis (1 paper, 2025). The growth of functional endometrial tissue in anatomic sites outside the uterine body. "A transcriptomic analysis revealed key miRNAs and lnCRNA implicated in endometriosis and RIF, including miR-9, miR-34, and miR-135a/b miR-30d-5p, PART1, MIR17HG, H19, LINC00173, NEAT1, and LINC01960-201." (PMID 39858500, 2025).